IGF1 (insulin like growth factor 1)
Diseases named in the same sentence as IGF1 in open-access papers (continued):
Sharing a sentence is not in itself a finding about the gene and the disease.
diabetes (continued). "Models of diabetes and hypertension suggest that IGF-1 can exert an anti-inflammatory role; higher IGF-1 levels protect against microvascular complications of hypertension and the development of type 2 diabetes mellitus." (PMID 33562271, 2021). "This manuscript gives an overview of the physiological actions of GH/IGF-1 on the kidneys and the multiple alterations of the GH/IGF-1 system and its consequences in patients with acromegaly, CKD, nephrotic syndrome, and type 1 diabetes mellitus." (PMID 34143299, 2021). "Bioinformatics studies on the expression profile of miRNAs in diabetes show that GLUT1-4 and IGF-1 mRNAs are potential targets of the miR-29 family." (PMID 33883592, 2021). "Our results indicate that diabetes significantly results in upregulation of the miR-29 family and downregulation of the GLUT1, 2, 3, 4, and IGF-1 genes." (PMID 33883592, 2021). "The recent Pituitary Society Guidelines suggest that patients with diabetes mellitus and those with a higher BMI require higher doses of PEGV and more rapid up-titration to achieve IGF1 normalization." (PMID 34342594, 2021). "However, GH/IGF1 excess could mask the ill effects of diabetes on periodontal health." (PMID 33154456, 2020). "For instance, the hallmark “deregulated nutrient signalling” refers to pathways that sense and respond to nutrient availability such as “insulin and IGF1 signalling” (IIS) pathway, which is altered in diabetes." (PMID 32363781, 2020). "An inverse relationship between the circulating levels of IGF-1 (IGF-ItoIGFBP-3 ratio) and MetS, diabetes, and CVD has been reported." (PMID 33905470, 2020). "However, the concurrent presence of diabetes could not exert any significant untoward effects on periodontal tissue in the presence of GH/IGF1 excess despite patients of acromegaly with diabetes had elevated levels of proinflammatory and decreased levels of antiinflammatory cytokines." (PMID 33154456, 2020). "The data showed that compared with the control group, the expression levels of CASP3, VCAM-1 and HGF were down-regulated in patients with syphilis and diabetes, while ALB, FN1, MMP9, IL8, CTGF, STAT3 and IGF1 were up-regulated." (PMID 32342229, 2020). "And it also provides evidences that among elderly with diabetes mellitus, oxidative damage and HCY as well as IGF-1 are important predictors of age-dependent sarcopenia." (PMID 33381601, 2020). "Out of these 15 predicted genes, we selected 4 target genes (IGF-1, SLC2a-12, EIF-4e, and ULK-2) based on the available literature related to myocardial function and/or diabetes for experimental validation." (PMID 30823517, 2019). "Insulin-like growth factor 2 (IGF2) can activate tyrosine kinase upregulation by binding to IGF1, and it also leads to a decrease in the activity of insulin receptor substrate (IRS1), which can result in the development of diabetes." (PMID 30131712, 2018). "IGF-1 is known regulator of Myocyte enhance factor 2C (MEF2C), which plays an active role in diabetes-provoked cardiac hypertrophy." (PMID 30013975, 2018). "Thus, identification of therapeutics that bias the IGF-1R to selectively activate Akt would address potential concerns that IGF-1 may exacerbate microvascular dysfunction in diabetes through ERK, as it can also play a role in VEGF-induced RNV since IGF-1-induced VEGF expression is ERK-dependent." (PMID 28796787, 2017). "VEGF also plays a pivotal role in diabetes that mediates the hyperglycemia-induced pathological effect by oxidative stress, which activates VEGF and IGF-1 signaling pathways via protein kinase C (PKC) and interrelated each other." (PMID 28191276, 2017). "In induced diabetes STZ mice, MSC helped to attenuate abnormal function of adipocytes, which are involved in cutaneous wound-healing, by IGF-1 secretion." (PMID 28298931, 2017). "In type 1 diabetes mellitus (T1DM), low concentrations of IGF1 and high concentrations of IGF-binding protein 1 (IGFBP1) have been reported." (PMID 24327601, 2014).
diabetes (continued). "In ERMs, IGF1 and IGF1R mRNA levels were significantly higher in patients with diabetes compared to control subjects." (PMID 24379526, 2013). "IGF1 levels were associated with neither severe hypoglycemia in the entire cohort (P=0.30) nor in any gender nor when confining the analysis to those with long-standing diabetes (>20 years) (n=112, P=0.68) and those with both long-standing diabetes and undetectable C-peptide (n=51, P=0.067)." (PMID 23781301, 2012). "In order to examine the relationship between PR-ASG and IGF-1, we determined how PR-ASG affects IGF-1 levels of serum, pancreas, and liver in STZ-diabetes rats fed PR diet." (PMID 22194889, 2011). "The protein IGF-1 was significantly (p < 0.001) decreased in diabetic rats (D group) compared to non-diabetes group rats and was not significantly changed (p = 0.82) in D-MET group rats compared to diabetic rats." (PMID 40362714, 2025). "Since diabetes mimics accelerated aging, geriatric T2DM patients show further IGF-1 reduction." (PMID 41393761, 2025). "This is further supported by acromegaly patients with excessive GH/IGF-1 levels showing increased retinal vessels and vascular branching points despite the absence of diabetes." (PMID 40362202, 2025). "For example, an 85-year-old CSVD male with no history of diabetes, clinical tests showed that C-peptide was 500 pmol/L, IGF-1 was 160 ng/mL, total cholesterol was 4.5 mmol/L, and imaging examination showed WMH." (PMID 39963470, 2025). "Their findings established that IGF-1 administration mitigated the negative effects of diabetes by accelerating tooth movement, promoting new bone formation, reducing the number of osteoclasts, and inhibiting the secretion of inflammatory factors." (PMID 40725571, 2025). "IGF-1 demonstrated negative correlations with age, duration of diabetes, fasting glucose, HbA1c, total cholesterol, triglycerides, low-density lipoprotein cholesterol (LDL-C), fasting insulin, HOMA-IR, and TNF-α." (PMID 41393761, 2025). "Disruption of the IGF-1–mTOR–IL-15 loop, which leads to the interruption of cellular interactions between DETCs and keratinocytes, also contributes to DETC dysfunction in obesity and diabetes." (PMID 39944225, 2025). "Furthermore, recent research provides support for the connection between type 2 diabetes mellitus (T2DM) and neurodegeneration through two key factors: the increase in proinflammatory cytokines and the onset of insulin/IGF-1 resistance." (PMID 38300646, 2024). "Additionally, a positive correlation between cord blood IGF-1 bioavailability and IVS thickness was observed in the newborns of mothers with diabetes." (PMID 38605306, 2024). "Moving on to the discussion of IGFs, we did not observe significant differences in the levels of both IGF1 and 2 between the cancer and control groups, after adjusting for BMI, diabetes, and parity." (PMID 38339282, 2024). "In a mouse pancreatic islet study, gene expression and protein levels of CCN5 were upregulated under the influence of IGF-1, leading to the activation of AKT and ERK2 and contributing to the growth and survival of pancreatic beta cells, thus improving the condition of diabetes." (PMID 37794318, 2023). "Moreover, TRF also reduced retinal expression of VEGF (p < 0.001), IGF-1 (p < 0.001) and HIF-1α (p < 0.05) compared to vehicle-treated rats with diabetes." (PMID 37268913, 2023). "25OHD had a stronger effect on IGF1 (P for interaction = 0.031) in patients with diabetes than in those without diabetes." (PMID 37072869, 2023). "Studies have reported the negative impact of TDF on the IGF-1 level in blood and brain samples and its implication in diabetes." (PMID 35122679, 2022). "We found that the histogram reflecting the number of subjects without diabetes showed a similar shape with IGF-1 SDS values peaking around − 1.5." (PMID 36418379, 2022). "If all this is true, then patients with acromegaly and diabetes should need higher GHRA doses to normalize IGF-1 compared to patients without diabetes." (PMID 35448486, 2022).
diabetes (continued). "In the present study, we established the diabetes model in C57BL/6J mice by streptozotocin (STZ) injection and showed that spinal IGF-1/IGF1R signaling and particularly microglial IGF-1 diminished along with pain-like behaviors, spinal neuroinflammation, and augmented M1 microglial polarization." (PMID 35401920, 2022). "The phenotype of diabetes by blocking IGF-1 signaling is more obvious in mouse models lacking both IGF1R and INSR in β-cells." (PMID 35370981, 2022). "Maternal IGF-1 and fetal IGF-1 have been associated with macrosomia, irrespective of maternal diabetes mellitus." (PMID 36001625, 2022). "Moreover, it is also intriguing to test the role of TXNIP in the prolonged IGF1-induced senescence phenotype since TXNIP is highly expressed in the late stages of aging and diabetes as an inflammatory marker and, conversely, as a tumor suppressor in cancer." (PMID 36291127, 2022). "The aim of this study was thus to assess the prognostic impact of DPP4i in patients with both diabetes and coronary artery disease (CAD) who underwent percutaneous coronary intervention (PCI) through the insulin-like growth factor-1 (IGF-1) axis, a substrate of DPP4." (PMID 35332212, 2022). "In particular, we found that serum IGF-1 and IL-6 levels were significantly lower in the control group than in the diabetes without nephropathy group, the macroalbuminuria group and the microalbuminuria group (P < 0.05)." (PMID 36568065, 2022). "The frequency of hypertension tended to be high in the low IGF-1 group (14 (82.4%) vs. 28 (59.6%), P = 0.26), while that of diabetes was not increased (12 (70.6%) vs. 34 (72.3%), P = 1.00)." (PMID 36418379, 2022). "Although we found that the IGF-1 level in the diabetes group was lower than that in the non-diabetic group, this was not statistically significant." (PMID 34690653, 2021). "We compared the levels of IGF-1 and sclerostin in premenopausal women with and without diabetes as potential markers of diabetoporosis in premenopausal women with diabetes." (PMID 34690653, 2021). "We considered, separately for men and women, potential mediating effects of the following variables: CRP, creatinine, vitamin D, calcium, ALP, IGF1, SHBG, testosterone, testosterone/SHBG, estradiol, phosphate, cystatin C, hypertension, diabetes, and hypercholesterolemia." (PMID 32964541, 2021). "Diabetes markedly decreased plasma insulin-like growth factor (IGF)-1 levels, while B12, but not N-acetyl-L-cysteine nor tempol, restored them." (PMID 34163008, 2021). "Taken together, these data led us to hypothesize that IGF-1 and/or IGF-2 may be important endogenous ligands of the retinal IR and play a critical prosurvival role in retinal neurons, a function disrupted by diabetes." (PMID 33915127, 2021). "Insulin and insulin-like growth factor-1 (IGF-1) have been demonstrated to induce chondrogenic differentiation and reduce the progression of IVD degeneration in vitro and in vivo, and also in animal models of type 2 diabetes mellitus." (PMID 33634362, 2021). "At year 1, the IGF1 normalization rate was slightly lower in patients with diabetes than those without (52.1% vs 57.4%)." (PMID 34342594, 2021). "IGF1 effects in the kidney are modulated by nitric oxide, and nitric oxide synthase inhibition reduced renal hypertrophy and hyperfiltration in STZ-induced diabetes mellitus rats." (PMID 34943879, 2021). "In addition, rats with 4 weeks of diabetes and age-matched controls have equivalent serum IGF-2 content, whereas mature IGF-1 is dramatically reduced in the same animals." (PMID 33915127, 2021). "For male RTR with higher levels of IGF1, subjects were more likely to be younger, to have a higher body weight and SQUASH score, and to have a lower waist circumference, prevalence of diabetes mellitus as primary renal disease, and cumulative prednisolone dose." (PMID 31973007, 2020).
diabetes (continued). "In our study, patients of acromegaly who had diabetes were older and had a higher BMI than acromegaly without diabetes regardless of GH/IGF1 levels and tumor volume." (PMID 33154456, 2020). "Age-adjusted fIGF-1 levels were much higher among diabetes patients with DR than in those without DR, but another study found no real connection between IGF-1 levels and the progression of retinal disease." (PMID 33905470, 2020). "Further, the active disease status was strengthened by age and sex-matched higher IGF1 levels (778.0 and 802.9 ng/ml, 2.5-fold higher than mean) though, was comparable in acromegaly patients with and without diabetes." (PMID 33154456, 2020). "High IGF-1 availability may defend against the onset of CVD and glucose intolerance in diabetes patients." (PMID 33905470, 2020). "The well-known inhibitors of IGF-1/PI3K/AKT/mTOR working as geroprotectors, metformin and rapamycin modulate immunity and protect against age-related diseases such as diabetes and cancer." (PMID 33333870, 2020). "His 59-year-old sister has a similar phenotype, and had generalized lipoatrophy since childhood, without diabetes or hypertension, and with normal IGF-1." (PMID 32079542, 2020). "However, diabetes patients are sensitive to the stimulation of side effects in response to IGF-1, which limits the practicality of IGF-1 as a hypoglycemic agent." (PMID 33905470, 2020). "Nevertheless, the patients with acromegaly having diabetes had modestly higher CAL and PD and serum IL-6 levels (p = 0.051), but it could not exert adverse effects on periodontal health in presence of GH/IGF1 excess." (PMID 33154456, 2020). "Adequate assessment has not been made of the predictive utility of IGF-1 for birthweight and macrosomia in women with diabetes." (PMID 30108547, 2018). "In addition, recent work supports the involvement of two key factors linking type 2 diabetes mellitus (T2DM) with neurodegeneration; the elevation of proinflammatory cytokines and the onset of insulin/IGF-1 resistance." (PMID 30026694, 2018). "Insulin-like growth factor-1 (IGF-1) and growth hormone levels in patients with (DM) and without (non-DM) diabetes mellitus were analyzed." (PMID 29767287, 2018). "The IGF-1 level thereafter tended to decrease, and at 48 months, the difference from diabetes diagnosis was no longer significant." (PMID 29744370, 2018). "In the epidermis, IL-15, IGF-1, and mTOR are known to regulate the maintenance of DETCs; however, it is unclear how these molecules may intersect to regulate DETC homeostasis in diabetes." (PMID 28729536, 2017). "In the current study, the IGFBP-7/IGF-1 ratio was significantly increased in patients with metabolic syndrome and/or diabetes compared to those without metabolic syndrome." (PMID 27769173, 2016). "The fifth macroadenoma was identified in a 68-year-old male patient with high IGF-1, well-controlled hypertension and diabetes mellitus and no other comorbidities or symptoms, who did not want to receive any treatment." (PMID 26186299, 2015). "Numerous growth factors such as insulin-like growth factor 1 (IGF-1), platelet-derived growth factor (PDGF), vascular endothelial growth factor (VEGF), and epidermal growth factor (EGF) contribute to the early proliferation of tubular system in diabetes." (PMID 26644877, 2015). "A low IGF-1 level does not exclude acromegaly in a patient with supportive clinical features and poorly controlled diabetes." (PMID 26514337, 2015). "Patients with diabetes also showed a significantly higher initial IGF-1 level, independent of therapy achieved targets." (PMID 25996963, 2015). "Diabetics showed significantly higher initial IGF-1 (389.38 vs. 285.27, p = 0.009), as did diabetics older than 50 compared with those without diabetes." (PMID 25996963, 2015).
diabetes (continued). "-mediated repression of IGF-1 signalling through PTP1B and PTEN activation might have salutary effects on cells with perturbed mitochondria as is the case in type 2 diabetes mellitus, ageing, impaired wound healing, and neurodegenerative disease." (PMID 25520316, 2015). "It has been reported that IGF-1 can be induced on certain circumstances, such as inflammatory bowel disease (IBD), myocardial infarction, growth hormone stimulation and diabetes." (PMID 25956506, 2015). "We then evaluated the effects of IGF1 (Insulin-like growth factor 1), IGF2 (Insulin-like growth factor 2), EGF (Epidermal Growth Factor) and glargine (an insulin analogue used in the treatment of diabetes) on PIP3 production in the MCF-7/B2 clone." (PMID 24647478, 2014). "Nonetheless, in the R6/2 HD mouse model, IGF-1 administration has been shown to lead to some beneficial effects, including protection against diabetes and hind-limb clasping, but not on motor function." (PMID 25140802, 2014). "Previous studies have demonstrated that the expression level of IGF1 and IGF1R decreased in brain tissue of diabetes, and disruption of the GIGYF2 gene in mice led to a decrease in IGF1-stimulated IGF1R tyrosine phosphorylation but an augmentation in ERK1/2 phosphorylation." (PMID 25268761, 2014). "IGF1 accumulates in the kidney soon after streptozotocin (STZ)-induced diabetes in rats and mice, but renal IGF1 expression is not usually increased, suggesting that the increased IGF1 is derived from the systemic circulation." (PMID 23781310, 2012). "Thyroid nodule (TN) prevalence is rising globally, with particularly high rates among patients with type 2 diabetes mellitus, where insulin resistance and hyperinsulinemia may promote nodule formation via the thyroid-stimulating hormone (TSH)/insulin-like growth factor-1 axis." (PMID 41650047, 2026). "Studies have shown that IGF-1 levels decrease in non-healing wounds of patients with diabetes." (PMID 39944225, 2025). "The insulin and insulin-like growth factor 1 (IGF-1) receptor, insulin receptor substrates 1 and 2 (IRS1/2), and important second messenger kinases like Akt and mTOR were all found to be inactivated in patient brain tissue, which is comparable to what is seen peripherally in diabetes." (PMID 40964464, 2025). "Furthermore, a lower serum IGF-1/IGFBP-3 molar ratio has been connected to poorer executive function in MCI patients, particularly those with type 2 diabetes mellitus (T2DM), suggesting that IGF-1 may play a role in the development of cognitive impairment." (PMID 40699632, 2025). "Taken together, the intricate relationship between IGF-1 and T2DM highlighted here warrants further exploration, as confirmation in larger longitudinal studies could open a new dimension in the management of diabetes in the aging global population." (PMID 41393761, 2025). "Therefore, diabetes appears to play a role in modulating IGF1 levels, although the results were not significant for the study population." (PMID 38339282, 2024). "Furthermore, the result of the subgroup analysis showed that 25OHD had a stronger effect on IGF1 in patients with diabetes than in those without diabetes." (PMID 37072869, 2023). "However, recent guidelines recommend IGF-1 level measurement to alsoinclude those without typical manifestations but with several atypical signs suchas sleep apnea, type 2 diabetes mellitus, debilitating arthritis, carpal tunnelsyndrome, and hypertension." (PMID 39076279, 2023). "The smooth curve produced using the generalized additive model demonstrated that after adjusting for age, sex, race, BMI, exercise, smoking behavior, alcohol intake, diabetes, and serum calcium level, the relationship between 25OHD and IGF1 was nonlinear, with an inverted U shape." (PMID 37072869, 2023). "Especially, the future incidence rates of diabetes in the low IGF-1 group without diabetes may merit investigation." (PMID 36418379, 2022).